IL6 (interleukin 6)
Diseases named in the same sentence as IL6 in open-access papers (continued):
Sharing a sentence is not in itself a finding about the gene and the disease.
Chronic colitis (67 papers, 2009 to 2025). A chronic inflammatory disease of the large intestine (colon, cecum and rectum). "Although we showed that blocking IL-17A function may be associated with upregulation of Il6 and recruits RORγt+ ILCs in chronic colitis models, the pathogenic relevance of these findings should be investigated further." (PMID 31941937, 2020). "Notably, MCJ-deficient mice displayed higher Il6 levels in chronic colitis compared to WT." (PMID 35705557, 2022). "In this study, we found that 5-ASA or monotropein remarkably decreased serum levels of TNF-a and IL-6 cytokines and increased levels of anti-inflammatory cytokine IL-10 in chronic colitis mice." (PMID 40041493, 2025). "Evidence suggests that IL‐6 is a key cytokine in chronic colitis, and reduced IL‐10 activity leads to increased levels of IL‐6, IFN‐γ, and TNF." (PMID 40953838, 2025). "In the present study, colonic inflammation was evident in mice with DSS-induced chronic colitis and elevated levels of IL-6 and IL-1β." (PMID 37695333, 2024). "In accordance with acute colitis, proinflammatory factor levels (e.g., IFN-γ, TNF-α, IL-17A, IL-1β and IL-6) were obviously elevated in chronic colitis mice compared to those of normal mice." (PMID 38396052, 2024). "From the perspective of cytokine expression, qPCR analysis demonstrated that the upregulation of Il1b, Tnfa, and Il6 were diminished in Tmem173iΔmye mice in both acute and chronic colitis." (PMID 39113810, 2024). "IL-6 is also involved in the progression of acute inflammation to chronic colitis and is upregulated in inflammation-related colon carcinogenesis." (PMID 39290583, 2024). "Cripto-1, as a multifunctional signaling molecule, exerts an extracellular immune effect through paracrine mode, such as regulating macrophage expression of proinflammatory cytokines TNF-α and IL-6, inducing chronic colitis." (PMID 36644162, 2023). "For mice with chronic colitis, plasma G-CSF and IL-6 were significantly increased in both females and males, while TNF-α and IL-17 levels were selectively increased in female mice." (PMID 35463755, 2022). "For mice with chronic colitis, plasma G-CSF and IL-6 were significantly increased in both females and males, while TNF-α and IL-17 were increased only in females." (PMID 35463755, 2022). "As expected, plasma levels of proinflammatory cytokines, including interleukin-6, interleukin-17, tumor necrosis factor alpha, and chemokine ligand 1, were significantly increased in the chronic colitis model." (PMID 36009796, 2022). "Fucoidan from seaweed Cladosiphon okamuranus improved chronic colitis by downregulating the expression of the proinflammatory cytokine IL-6 in the colonic epithelial cells of IBD mice." (PMID 33671085, 2021). "We thus suggest that M10 treatment result to the prevention of the pathogenesis of chronic colitis, probable due to the regulatory effects of IL-6/NF-κB signaling pathways in the inflamed colonic epithelium." (PMID 33041798, 2020). "Excessive activation of STAT3 mediated by increasing IL-6 enhances the expression of antiapoptotic factors such as Bcl-2, which contributes to the sustainability of chronic colitis." (PMID 30498394, 2018). "The IL6ST/gp 130 is known to regulate transduction of proinflammatory cytokines, i.e., IL-6 and IL-27, which their increased production has been reported in CD patients with chronic colitis." (PMID 27065983, 2016). "Polysaccharide-peptidoglycan complex derived from Lactobacillus casei strain Shirota inhibited the release of IL-6 in LPS-stimulated large intestinal lamina propria mononuclear cells isolated from mice with chronic colitis and in RAW264.7 cells in vitro." (PMID 27756217, 2016). "In the chronic colitis model, a decreased production of IL-6 in DSS/6-TG 20 treated mice as compared to either DSS/PBS- or DSS/AZA 60-treated mice was observed." (PMID 21545711, 2011).
Chronic colitis (continued). "Conversely, both 5-ASA and monotropein could substantially decrease the expression of TNF-α and IL-6 and increase the expression of IL-10 in mice with chronic colitis." (PMID 40041493, 2025). "Additionally, in dextran sodium sulfate-induced chronic colitis mouse, fucoidan ameliorated chronic colitis by inhibiting IL-6 production in colonic epithelial cells." (PMID 39590766, 2024). "Furthermore, COSLow restored the altered microbiome in the gut and inhibited the elevated pro-inflammatory cytokines (IL-1 and IL-6) in the colon against DSS-induced chronic colitis in mice." (PMID 37695333, 2024). "In particular, the application of fucoidan can diminish mucosal damage and crypt destruction in the murine chronic colitis model, while the fucoidan from C. okamuranus suppressed the expression of pro-inflammatory cytokine IL-6 in the epithelial cells which improved chronic colitis in mice with IBD." (PMID 36233121, 2022). "In addition, CHST15 siRNA reduced serum IL-6 level and the excessive accumulation of macrophages that was distinct from chronic colitis." (PMID 27410685, 2016). "Moreover, CR attenuated chronic colitis in mice in a dosing time-dependent manner based on measurements of disease activity index, colon length, malondialdehyde/myeloperoxidase activities and IL-1β/IL-6 levels." (PMID 34393786, 2021). "Moreover, as shown by immunostainting, an elevated expression of the proinflammatory cytokine IL-6 [which is tightly implicated in the pathogenesis of human and experimental chronic colitis] was observed in DSS chronic colitis model in colons of Sdc1-KO as compared to wt mice." (PMID 28350804, 2017). "Similarly to previous reports, progression from acute to chronic colitis in wt mice was associated with a reduced expression of IFNγ and IL-6, accompanied by an increased (albeit not significant) IL-10 levels." (PMID 20706593, 2010). "After the induction of chronic colitis, a substantial elevation in the levels of iNOS, COX-2, TNF-α, IL-6, and IL-1β were observed in this study." (PMID 37891901, 2023). "In contrast, the absence of miR-155 overexpression in the sigmoid colon of PSC-UC patients activated the Il-6/S1PR1 signalling pathway and imbalanced the IL17/FOXP3 ratio, which reinforces chronic colitis." (PMID 35563301, 2022). "In a mouse model of chronic colitis, treatment with fucoidan (Cladosiphon okamuranus Tokida) inhibited the activation of NF-κB pathway, thereby suppressing IL-6 synthesis and down-regulating IFN-γ expression to improve chronic colitis in rats." (PMID 36142699, 2022). "The effect of CR on chronic colitis was accessed based on DAI, colon length, MDA/MPO activities and IL-1β/IL-6 levels as well as histopathological analysis." (PMID 34393786, 2021). "The mRNA expression levels of inflammatory cytokines including IFN-β, IL-1β, IL-6, iNOS, MCP-1, and TNF-α were high in AOM+DSS induced chronic colitis group." (PMID 33995655, 2021). "The intervention of TFA increased the levels of IL-10 and TGF-β, and downregulated the expression of pro-inflammatory factors IL-17, IL-6, TNF-α, and IFN-γ in TNBS-induced chronic colitis." (PMID 35002710, 2021). "IL-6/STAT3 was also demonstrated to be involved in metabolic reprogramming, to promote the progression from chronic colitis to CRC, and the COX-2/PGE2 pathway was also shown to contribute to inflammation and carcinogenesis in IBD." (PMID 31523496, 2019). "Levels of the inflammatory cytokinesTNF-α, IL-1β, IL-6, MCP-1, and CSF-1 and of COX-2 were measured in mice with chronic colitis." (PMID 29245972, 2017). "Colorectal mRNA levels of inflammatory cytokines TNF-α, IL-1β, IL-6, MCP-1, and CSF-1, and COX-2, were measured in mice with chronic colitis." (PMID 27557503, 2016). "Indeed, a recent study reported that animals with chronic colitis had a parallel increase in the cytokine levels of TNF-alpha, IL-1-beta, IL-6 and IL-10 in their blood and hippocampus." (PMID 35269413, 2022).
Chronic colitis (continued). "The data from the present study also showed that the plasma levels of proinflammatory cytokines, G-CSF, IL-6, IL-17, TNF-α, and CXCL1, were significantly increased in mice with chronic colitis, suggesting the presence of significant systematic inflammation in mice with chronic colitis." (PMID 36009796, 2022). "Secondly, in the absence of miR-155 over-expression, the activated IL-6/S1PR1 signalling pathway reinforced chronic colitis in the sigmoid colon of PSC-UC patients." (PMID 35563301, 2022). "Detection of the cytokine concentrations in the supernatant (five samples per group) revealed that IL-1β, IL-6, IL-12p70, TNF-α, and IL-23 were significantly decreased in the chronic colitis + Se-enriched L. acidophilus group compared with the chronic colitis group (P < 0.05)." (PMID 34532332, 2021). "In the present study, significant increases in the production of IL-6, IL-12p70, IL-1β, TNF-α, IFN-γ, IL-21, and IL-17A and decreases in the production of IL-10 were observed in the chronic colitis group compared with the control group, and these changes were restored by NAM treatment." (PMID 33748287, 2021). "In our results, we established a refined and translationally relevant model of DSS chronic colitis in C57BL/6 mice and found morbidity in liver morphology and significant increases in proinflammatory cytokines (TNF-α, IL-1β, and IL-6) in the liver tissue of IBD mice." (PMID 33029104, 2020). "Measurement of cytokine concentrations in the culture supernatants of the MLN without any stimulation manifested that the levels of IL-6, IL-1β, and IL-23 were sharply decreased in the IL-33-treated chronic colitis group compared with the control group." (PMID 30539029, 2018). "Therefore epithelial cells of chronic colitis and CAC are thought to be in a state more suitable for the receiving of IL-6 trans-signaling than the canonical IL-6 signal pathway." (PMID 27350830, 2016). "Similarly to what has been reported for several experimental models of acute and chronic colitis, local NO-production drives an increased expression of TNF-α, IFN-γ and IL-6." (PMID 24873968, 2014). "Another in vitro study of chronic colitis model showed that earlier administration of citropten/ limettin reduced NF-κB and MAPK signaling pathway occurring in epithelium of intestine and triggered T cells, in addition to reducing IL-6 in vascular inflammation model." (PMID 40381124, 2025). "In addition, our study revealed a negative correlation between the levels of β-hydroxybutyrate in rats with chronic colitis and proinflammatory cytokines such as TNF-α, IL-6, IL-1β, and IL-18, with a strong tendency towards a positive correlation with IL-10 levels." (PMID 37513865, 2023). "Besides TNF-α, another inflammation factor, IL-6, whose expression was elevated in macrophages with AEG-1 overexpression, was also reported contributing to the creation of an inflammatory environment and resulting in a chronic colitis and invasive colonic adenocarcinomas." (PMID 27793010, 2016). "In chronic colitis (63 days), MP did not affect the TNF-α, IL-β, IL-6 and IL-10 blood levels, which is consistent with our data." (PMID 40863977, 2025).
memory impairment (67 papers, 2012 to 2025). "In this work, LPS has been found to be a contributing factor in learning and memory impairments; a finding associated with an increase in the amount of IL-6 and TNF-α, but a drop in IL-10 of the hippocampus." (PMID 31579451, 2019). "IL-6 had facilitating effects on IL-1β in mediating inflammation and causing hippocampal-dependent memory impairment." (PMID 24236147, 2013). "Besides, IL-6 promotes IL-1β mediated inflammatory responses that cause hippocampus-dependent memory impairment." (PMID 38082215, 2023). "Previous studies showed that pro-inflammatory cytokines, such as TNFα, IL6, and IL1β, could potentially disturb the Aβ clearance and cause memory impairments." (PMID 32867800, 2020). "In addition, IL-6 facilitates the effect of IL-1β in mediating inflammation and causing hippocampal-dependent memory impairment." (PMID 29137628, 2017). "IL-6 contributes to memory impairment, glucose metabolism dysregulation, tau hyperphosphorylation, brain cell aging, and the production of other pro-inflammatory factors." (PMID 40563297, 2025). "IL-6 resulted in memory impairment, as inhibition of IL-6 enhanced long-term potentiation and improved long-term memory in a hippocampal-dependent task." (PMID 39891777, 2025). "Our research findings suggested that learning and memory impairment induced by NDEA was associated with high levels of Aβ1-42, TNF-α, and IL-6 in the hippocampus, and these effects were recovered by metformin." (PMID 37759689, 2023). "Inhibition of pSTAT3 signaling, affecting IL-6 signaling, in the brains of AD mice was demonstrated to reduce memory impairments." (PMID 35648273, 2022). "It has been found that berberine can reduce the levels of NF-κB, TLR4, TNF-α, and IL-6 in the brain of adult male cognitive impairment rats induced by lipopolysaccharide and prevent learning and memory impairment." (PMID 35795239, 2022). "Recently, we reported that, in adult male wild-type mice subjected to tibial fracture under general anesthesia, IL-6 trans-signaling in hippocampal CA1 neurons mediates surgery-induced memory impairment." (PMID 36778590, 2022). "Proinflammatory cytokines such as IL-6 and oxidative stress play pivotal roles in neurodegeneration and memory impairment." (PMID 32802263, 2020). "Especially, IL-6 is known to activate STAT3, which is associated with memory impairment in the LPS-injected IL-6 KO mice." (PMID 30781690, 2019). "We showed that treatment with IFNβ1a was able to reverse memory impairment and to counteract microglia activation and upregulation of pro-inflammatory cytokines (IL-6, IL-1β) in the hippocampus of Aβ1-42-injected rats." (PMID 30777084, 2019). "The short treatment with IFNβ1a was able to reverse memory impairment and to suppress microglia activation and the upregulation of pro-inflammatory cytokine (IL-6, IL-1β) levels and oxidative stress in the hippocampus." (PMID 30777084, 2019). "In this study, SPS induced an increase in the levels of the proinflammatory cytokines TNF-α and IL-6 and produced learning and memory impairment." (PMID 29973144, 2018). "Blocking these exaggerated effects, specifically by decreasing the release of tumor necrosis factor α (TNF-α), interleukin 1β (IL-1β), and interleukin 6 (IL-6), has been shown to prevent inflammation-induced memory impairment." (PMID 29167670, 2017). "Inflammatory cytokines, including IL-6, IL-1β, and TNF-α, have been reported to be associated with learning and memory impairment." (PMID 28373844, 2017). "We therefore have reason to believe that the brain levels of Aβ, P-tau protein, IL-6, and ACh mark early events in memory impairment." (PMID 26271247, 2015). "In another study, using low-dose lipopolysaccharide challenge, declarative memory impairment was also inversely correlated with IL-6 levels." (PMID 24534013, 2014).
memory impairment (continued). "Our previous studies showed that GBE50 prevented age-related learning and memory impairment and reduced the expression of several proinflammatory cytokines, including IL-1β and IL-6, in hippocampal cells." (PMID 24782908, 2014). "For instance, it has been shown that TNF-α and IL-6 are critical for neuroinflammation-induced memory impairment." (PMID 24886300, 2014). "Overproduction of IL-6 and TNF-α were related to memory impairment, which were considered a histopathological hallmark of various neurological diseases in the brain." (PMID 24422705, 2014). "LPS also successfully induced memory impairment in the Y maze test, neuroinflammatory responses, and oxidative stress such as increases in mRNA levels of interleukin (IL)-1β and IL-6, heme oxygenase-1, microglial activation, and iNOS activity in hippocampus." (PMID 24999480, 2014). "KXRG has significant effects on both local and systemic inflammatory responses, at least in part through selectively targeting COX-2 and IL-6; it prevents LPS-induced tissue damage in the small intestine, liver, and kidneys, and reduces memory impairments and neuroinflammatory responses." (PMID 35408453, 2022). "Targeting pro-inflammatory IL-6 signaling may be a strategy to alleviate memory impairment and metabolic alterations in the disease." (PMID 33911072, 2021). "IL-6, IL-1β, and TNF-α have been reported to be associated with learning and memory impairment." (PMID 28373844, 2017). "The role of IL-1β and IL-6 in surgery-induced learning and memory impairment has been indicated." (PMID 24884762, 2014). "Memory impairment; notable neuroinflammation, including astrocyte and microglial activation; and elevated protein levels of IL‐1β, TNF‐α, and IL‐6 in the hippocampus were detected in the Pg and Pg OMV groups." (PMID 39932228, 2025). "Several studies have revealed that inflammatory cytokines like interleukin-6 (IL-6) and tumor necrosis factor-alpha (TNF-alpha) significantly affect memory impairment." (PMID 39906616, 2025). "Salidroside potentially reduces hippocampus-dependent memory impairment by reducing Aβ1-42 deposition, microglial activation, and expression of proinflammatory factors, such as TNF-α, IL-6, and IL-1β, in the brain." (PMID 36014776, 2022). "Mice in the laparotomy group displayed memory impairment up to POD 14 with initial high levels of inflammatory cytokines in the liver, frontal cortex (IL-1β, IL-6, and TNF-α), and hippocampus (IL-1β and IL-8)." (PMID 29776428, 2018). "Microglial activation stimulates the accumulation of pro-inflammatory cytokines, such as IL-1β, IL-6, and TNF-α, which are responsible for memory impairment induced by LPS." (PMID 27803668, 2016). "However, recent research has shown that the neutralization of IL-6 and the inhibition of the STAT3 signaling pathway in the brain of AD mouse models can improve memory impairment." (PMID 39286235, 2024). "A study observed the IL-6 pathway activation in the hypothalamus and hippocampus in AD model mice, while inhibiting the signal transducer and activator of transcription 3 (STAT3) ameliorates memory impairment and reduces plasma IL-6 levels." (PMID 36293430, 2022). "Administration of Hyper IL-6, the selective IL-6 trans-signaling agonist, upregulated hippocampal pSTAT3 and induced memory impairment in the global absence of IL-6Rs, an essential component for classic signaling." (PMID 36778590, 2022). "Interestingly, similar to IL-6 and IL-18, TNF-α is also a product of activated microglia and is known to enhance memory impairment in mouse models of AD." (PMID 35648273, 2022). "This study demonstrated that AH might ameliorate the scopolamine-induced memory impairment by protecting the cholinergic system via inhibition of NF-κB signaling pathways and decreased levels of TNF-α and IL-6 in liver tissue." (PMID 34445062, 2021).
memory impairment (continued). "It significantly modulated the oxidative stress markers (SOD, GSH, CAT, MDA, and NO), inflammatory cytokines (IL-6, IL-1β, TNF-α), neurotrophic factors (CREB, BDNF), apoptotic markers (NFkB, caspase-3, caspase-9), and neurotransmitters (NE, DA, and GABA) in METH-induced memory-impaired rats." (PMID 41010958, 2025). "In a series of genetic and pharmacologic techniques in adult non-vulnerable mice, it was recently reported that IL-6 trans-signaling in hippocampal CA1 neurons is responsible for postoperative memory impairment; the key findings in this study are depicted in and are now laid out in further detail." (PMID 36778590, 2022). "Similarly, our findings indicated that MISO significantly increased the levels of pro‐inflammatory factors (IL‐6, IL‐1β, and TNF‐α) and decreased that of the anti‐inflammatory factor IL‐10 in the hippocampus of offspring mice, which contributed to the observed spatial learning and memory impairment." (PMID 38945806, 2024).